IL2RG (interleukin 2 receptor subunit gamma)
Diseases named in the same sentence as IL2RG in open-access papers (continued):
Sharing a sentence is not in itself a finding about the gene and the disease.
breast carcinoma (9 papers, 2012 to 2024). "Gene expression analysis from in vitro mammosphere formation revealed IFNG, CXCR5, CD40LG, TBX21, and IL2RG to be associated with the CSC phenotype and also displayed prognostic value for patients with breast cancer." (PMID 39001456, 2024). "Gene expression analysis revealed IFNG, CXCR5, CD40LG, TBX21 and IL2RG to be associated with the CSC phenotype and also displayed prognostic value for patients with breast cancer." (PMID 38831317, 2024). "The results revealed an insignificant increase in the IL2RG level in patients with breast cancer compared to controls (p = 0.657)." (PMID 37240365, 2023). "We orthotopically injected human breast cancer cells (SUM159PT) to mammary fat pads of NOD‐Scid IL2Rg‐null (NSG) mice, allowed tumors to develop to ~250 mm3, and then systemically injected 60 U ASNase per day for 5 consecutive days." (PMID 31523835, 2019). "Besides, HECTD3, PSMB10, UBD, UBE2C, and UBE2S involved in the ubiquitin proteasome pathway, as well as CCL2, CCR1, CXCL10, CXCL11, and IL2RG implicated in the cytokine–cytokine receptor interaction pathway, might be used for evaluating the efficacy of neoadjuvant chemotherapy in breast cancer." (PMID 29685151, 2018). "All Rag2−/−;Il2rg−/− mice inoculated i.v. with MDA-MB-453 breast cancer cells developed large ovarian metastases, frequently affecting both ovaries." (PMID 23382683, 2013). "In contrast, brain metastases were common in Rag2−/−;Il2rg−/− implanted with HER-2+ mammary carcinoma cells, making the Rag2−/−;Il2rg−/− mouse an exquisite model for the study of brain dissemination." (PMID 22737248, 2012). "Interestingly, comparison between the two cancer types revealed a highly significant reduction in the level of IL2RG in patients with ovarian cancer compared to those with breast cancer (p = 0.0027)." (PMID 37240365, 2023). "Our findings show that, although there was an insignificant increase in IL2RG in patients with breast cancer compared to controls, the level of this gene was significantly reduced in patients with ovarian cancer compared to controls and patients with breast cancer." (PMID 37240365, 2023). "What is more, the dysregulated genes IL2RG, IL6R, IL7R and TGFB2 have been reported to be associated with metastasis site or prognosis, and CCR6 is associated with both live metastasis in breast cancer and bone metastasis in human neuroblastoma." (PMID 25163697, 2014). "Therefore, CCL2, CCR1, CXCL10, CXCL11, and IL2RG might be involved in neoadjuvant chemotherapy in breast cancer via the cytokine–cytokine receptor interaction pathway." (PMID 29685151, 2018). "In fact, some immune related genes are essential in bone metastasis of breast cancer, and their family members, such as FAS, IL2RG and IL7R, have shown dysregulated in our work and have been reported to be either metastasis related or bone metastasis related." (PMID 25163697, 2014). "Human HER-2+ breast cancer cell lines MDA-MB-453 and BT-474 injected into Rag2−/−;Il2rg−/− mice faithfully reproduced human cancer dissemination, with multiple metastatic sites that included lungs, bones, brain, liver, ovaries, and others." (PMID 22737248, 2012).
melanoma (9 papers, 2020 to 2025). A malignant, usually aggressive tumor composed of atypical, neoplastic melanocytes. "The number of tumor-causing melanoma cells was significantly increased in Il2rg(-/-) mice with interleukin-2 receptor γ -chain deletion." (PMID 40019657, 2025). "To ascertain the suitability of mitf−/−/prkdc−/−/il2rg−/−Xenopus tropicalis for tumor allotransplantation, we conducted allotransplantations of xanthophoromas and melanomas in these amphibians." (PMID 38443437, 2024). "CSPG4-expressing A375 human melanoma xenografts implanted in NOD-scid IL2rg-/- mice were also engrafted with human immune cells by intravenous administration." (PMID 34513315, 2021). "A tetrad of IL2RA, IL2RG, IFNG, and IL7R genes were determined as hub genes and verified by qRT‐PCR, which were significantly associated with unfavorable prognosis in melanoma." (PMID 34159752, 2021). "The H&E results showed that the engrafted human melanoma tumours showed scant infiltration by porcine lymphocytes, indicating that IL2RG−/Y pigs were unable to reject the solid human tumours." (PMID 32871045, 2020). "Overexpressed IL2RA, IL2RG, IFNG, and IL7R were identified as the hub genes associated with melanoma metastasis, and may promote melanoma progression through activation of JAK—STAT signaling pathway." (PMID 34159752, 2021). "IL2Rg may also be an important immunotherapy target for melanoma." (PMID 40019657, 2025). "However, there still exist no reports on whether IL2RG is abnormally expressed and what influence ectopic IL2RG expression levels may exert in melanoma." (PMID 34159752, 2021). "Several studies have demonstrated that elevated levels of IL2RG as well as genes such as IL2RA, IL7R and IFNγ can promote melanoma metastasis by increasing intratumoral regulatory T cells through activation of the JAK-STAT signaling pathway." (PMID 40096084, 2025). "aceNKPs (CD45.2) were adoptively transferred intravenously into sublethally irradiated Rag2–/–Il2rg–/– (CD45.1) recipients and after ~6 wk these mice were challenged with the B16F10 melanoma cell line." (PMID 36442116, 2022). "Another relevant finding in this study was that overexpressed Treg cells in metastatic melanoma as compared with that in primary melanoma, were the pivotal intermediate components by which IL2RA, IL2RG, IL7R, and IFNG exert their immunosuppressive effect." (PMID 34159752, 2021). "And regulatory T‐cell proportion was indeed critically elevated in metastatic melanoma relative to primary melanoma, as well as in highly expressed IL2RA, IL2RG, IL7R, and IFNG group than their respective counterparts." (PMID 34159752, 2021). "Our study revealed that IL2RA、IL2RG, IFNG, and IL7R were hub genes in melanoma metastasis and involved in JAK—STAT signaling pathway that was identified as an central signaling pathway in metastatic melanoma, which was rarely illustrated in previous studies." (PMID 34159752, 2021). "Collectively, our findings underscored the core position of IL‐2RA, IL‐2RG, IFNG, IL‐7R, and JAK—STAT pathway in melanoma metastasis." (PMID 34159752, 2021). "Elevated IL2RA, IL2RG, IL7R, and IFNG expression may play a central role in promoting melanoma metastasis via increase in intratumoral regulatory T cell proportion, mainly by activation of the JAK–STAT signaling pathway." (PMID 34159752, 2021). "Elevated IL2RA, IL2RG, IL7R, and IFNG expression may play a central role in promoting melanoma metastasis through up regulation of intratumoral regulatory T—cell proportion mainly by activation of JAK—STAT signaling pathway." (PMID 34159752, 2021).
primary immunodeficiency (9 papers, 2017 to 2025). "X-linked severe combined immunodeficiency disease (X-SCID) is a form of inborn errors of immunity (IEI) associated with causal DNA variants of the IL2RG gene." (PMID 39822469, 2024). "A gene cluster centered on IL2RG was associated with several components of the Jak-Stat signaling pathway (p = 0.0002, Benjamini = 0.002), primary immunodeficiency (p = 0.008, Benjamini = 0.03), and cytokine-cytokine receptor interaction (p = 0.006, Benjamini = 0.06) pathways." (PMID 28279172, 2017). "The pathway analysis showed that IL2RG was involved in primary immunodeficiency and cytokine-cytokine receptor interaction." (PMID 34525985, 2021). "For example, several immunodeficient rabbit lines have been produced by knocking out of genes such as Il2rg, Foxn1, and Rag2; these animals are expected to make valuable contributions to regenerative medicine, cancer and primary immunodeficiency, as comprehensively reviewed elsewhere." (PMID 33584832, 2021). "The SGM rabbits we produced in this study can be used for modeling corresponding human primary immunodeficiency diseases: FOXN1 (OMIM# 600838), IL2RG (OMIM# 300400), RAG2 (OMIM# 601457), and PRKDC (OMIM# 600899)." (PMID 28939872, 2017).
pancreatic cancer (8 papers, 2017 to 2025). "In 2017, Ayars and al, using CRISPR-mediated knockout of IL2RG in orthotopically implanted pancreatic cancer cells, observed a reduction in tumor growth in mice and decreased JAK3 in orthotopic tumors." (PMID 40096084, 2025). "In another study, a transcript characterization of pancreatic intraepithelial neoplasia (PanINs) and normal pancreatic duct samples through RNA-seq revealed that IL-2RG overexpression played a role in the in vivo growth of pancreatic cancer cells." (PMID 38720389, 2024). "Here, we establish an orthotopic porcine model of human pancreatic cancer using RAG2/IL2RG double-knockout immunocompromised pigs and treat the tumors ex vivo and in vivo with histotripsy." (PMID 37596154, 2023). "For tumor engraftment, we have evaluated tumor progression of the following human cancer cell lines in the RAG2/IL2RG knockout pigs: PANC-1 (pancreatic cancer); HepG2 (liver cancer); and U-251 (brain cancer)." (PMID 34478363, 2022). "In tissue samples from patients with SD or PD, IL2RG (IL-2 receptor subunit gamma) was differentially expressed after treatment, which was previously identified to contribute in pancreatic cancer growth." (PMID 33428680, 2021). "CRISPR-mediated knockout of IL2RG in orthotopically implanted pancreatic cancer cells resulted in attenuated tumor growth in mice and reduced JAK3 expression in orthotopic tumors." (PMID 29137350, 2017). "To test whether the hamster is indeed a suitable host for human PDX, we carried out human pancreatic cancer cell transplantation experiments in the IL2RG KO hamsters and produced the first hamster PDX model." (PMID 35954238, 2022). "We first performed subcutaneous xenotransplantation of a human pancreatic cancer cell line, MIA-PaCa-2, into ZZU001 hamsters, and for comparisons, also into immunodeficient B-NDG (NOD-Prkdcscid IL2rgtm1/Bcgen) mice which are defective in both the IL2rg gene and the Prkdc gene." (PMID 35954238, 2022).
colitis (6 papers, 2012 to 2024). Inflammation of the colon. "When activated ILC1s and ILC3s were adoptively transferred into DSS-induced colitis Rag1-/-Il2rg-/- (ILCreg deficient) mice, severe colitis resulted, an effect that was attenuated upon ILCreg reconstitution." (PMID 36275689, 2022). "The use of Il2rg−/− rats reproduces a classical model of colitis in both immunodeficient mice (nude or different mutations in Rag or Il2rg genes) and rats (nude)." (PMID 36030499, 2022). "A significant up-regulation of genes encoding the following cytokines and their receptors—Il13, Il16, Il27, Il2rb, Il2rg, Il6r Il10ra, Faslg, Ltb, Osm, Spp1, Tnf, Tnfsf14—was noted in animals with colitis (CβG−)." (PMID 31590413, 2019). "Similar to the situation in Il2rg−/− mice, which are unable to signal through IL-7R, specific IL-7R blockade significantly diminished colonic ILCs and suppressed colitis." (PMID 23063332, 2012). "To investigate the effects of B/T/ILCs in liver injury‐aggravated colitis, we administrated CCl4, along with or without NMN supplementation, to mice lacking T and B cells (Rag2–/–) or those deficient in T, B cells, and ILCs (Rag2–/–Il2rg–/–), followed by DSS feeding." (PMID 39119946, 2024).
Opportunistic infection (6 papers, 2016 to 2026). An infection that is caused by a pathogen that would generally not be able to cause an infection in a host with a normal immune system. "Both FOXP3 and RORγt were undetectable in three patients with IL2RG, RAG1 and STAT1 mutations, implying that Treg and Th17 cells were almost completely absent, and therefore they had increased risks of developing autoimmune disorders and opportunistic infections." (PMID 32670274, 2020).
gastric cancer (5 papers, 2018 to 2025). A primary or metastatic malignant neoplasm involving the stomach. "IL2RG encodes for a subunit of the interleukin-2 receptor complex, which regulates T-cell function, was previously linked to poorer prognosis in gastric cancer, and IL2Rγ/JAK3 signaling has been shown to contribute to pancreatic cancer proliferation in vivo." (PMID 39796775, 2025). "We also verified our findings in datasets from the GEO database and confirmed that IL2RG is overexpressed in patients with gastric cancer and is associated with poor survival." (PMID 33542731, 2021). "A separate investigation disclosed the upregulation of IL-2RG in gastric cancer (GC) tissues, with high IL-2RG levels predicting a poorer OS." (PMID 38720389, 2024). "Similarly, IL2RG was found highly expressed in gastric cancer samples compared with normal samples in the GSE29272 dataset." (PMID 33542731, 2021). "Recent studies have also focused on tumor promotion in gastric cancer and potential targets for treatment, including MGST1, TTPAL, FBXO11, and IL2RG." (PMID 40186098, 2025). "Results showed striking elevations of IL2RG both in the mRNA and protein levels in GC tissues and human gastric cancer SGC-7901 cell line compared, respectively, with the adjacent normal gastric tissues and normal GES-1 cells, and higher IL2RG expression was associated with lower survival." (PMID 33542731, 2021).
T-cell leukemia (5 papers, 2009 to 2025). A malignant disease of the T-lymphocytes in the bone marrow, thymus, and/or blood. "The efficiency of the vectors in driving expression of IL2RG mRNA and protein expression was first tested using T cell leukemia cell line ED7R cells deficient in IL2RG." (PMID 40092492, 2025). "Unfortunately, five of these patients have developed T-cell leukemia two or more years after receiving the therapeutic gene IL2RG on a retroviral vector." (PMID 19461887, 2009). "Enforced expression of Il2rg has been shown to cause T-cell leukemias without gross overexpression." (PMID 19461887, 2009).
acute lymphoblastic leukemia (4 papers, 2010 to 2024). Leukemia with an acute onset, characterized by the presence of lymphoblasts in the bone marrow and the peripheral blood. "Furthermore, we established human acute lymphoblastic leukemia xenograft rat model by intravenously injecting 5.0 × 106 cells/kg of NALM6 cells into Il2rg/Rag2 KO rats." (PMID 39731164, 2024).
antibody deficiency (4 papers, 2021 to 2025). "Herein we explore the functional alteration of the hemizygous variant c.172C>A, p.(Pro58Thr) in IL2RG found in an adult patient who has been followed-up at our Clinical Immunology department for more than three decades for a CVID-like antibody deficiency with low T CD4+ counts." (PMID 40170851, 2025). "Normal T- and B-cell proliferation has been reported in a patient with the IL2RG variant p.(Asp134Val), who also suffers from CD4+ lymphopenia and antibody deficiency." (PMID 40170851, 2025). "Hypomorphic mutations in other IEI genes (BTK, GATA2, IL2RG, JAK3, RAG1, RAG2, etc.)have been previously found in patients with antibody deficiency and milder phenotypes or in CVID patients." (PMID 34975878, 2021). "Furthermore, memory B cell formation, humoral immunity and hypogammaglobulinemia were not restored by HSC transplant of patients with IL2RG variants who retained their own γc-deficient B cells but engrafted donor (IL2RG WT) T cells after transplant." (PMID 37273190, 2023).
autoimmune disease (4 papers, 2021 to 2025). A disorder resulting from loss of function or tissue destruction of an organ or multiple organs, arising from humoral or cellular immune responses of the individual to their own tissue constituents. "These genes included IL2RG and IL32, which are linked to autoimmune diseases, and IL7R, which is the most prominent example of a risk allele-associated alternatively spliced gene in MS." (PMID 40943121, 2025).
ovarian carcinoma (4 papers, 2010 to 2024). A malignant neoplasm originating from the surface ovarian epithelium. "Since X-SCID mice cannot reject transplanted tissues from other species including humans, we tested Il2rg-deficient rats as a host for xenotransplantation of human ovarian cancer tumor cells." (PMID 20111598, 2010). "Additionally, the function of SNK cells against ascites caused by ovarian cancer in NOD‐Prkdc(em26Cd52)il2rg(em26Cd22)/Nju (NCG) mice was determined." (PMID 38270321, 2024). "The human ovarian carcinoma SK-OV-3 cells implanted intraperitoneally (i.p.)in immunodeficient Rag2−/−;Il2rg−/− mice gave rise to a progressive peritoneal carcinomatosis which mimics the fatal condition in advanced human patients." (PMID 23382683, 2013). "However, there was a significant decrease in the level of IL2RG in patients with ovarian cancer (p = 0.020)." (PMID 37240365, 2023).
asthma (3 papers, 2011 to 2023). "miR-28-5p is a validated regulator of IL2RG (interleukin 2 receptor, gamma), which is a pro-inflammatory cytokine receptor that plays an important role in glucocorticoid function in severe asthma." (PMID 37296627, 2023). "We speculate that IL2RG and CCL4, which are also involved in this pathway, might be critical genes related to childhood specific asthma, and together with CCL2 play a role in this disease." (PMID 34525985, 2021).
atherosclerosis (3 papers, 2016 to 2023). A disease characterized by the build-up of fatty material and calcium deposition in the arterial wall resulting in partial or complete occlusion of the arterial lumen. "BALB/c mice homozygous for targeted immunological mutations like Rag1-knockout, Rag2-knockout and the Il2rg-knockout are suitable recipients for human hematopoetic stem cells and therefore the study of atherosclerosis in humanized mice." (PMID 27564380, 2016). "A previous study has shown that the elevated NK cells via adoptive transfer doubled atherosclerotic lesion size in ApoE-/-Rag2-/-IL2rg-/- mice, indicating that SnPP can exacerbate atherosclerosis through NK cells." (PMID 35281895, 2022). "In addition to Dpp4, there was an upregulation of a number of inflammation‐related genes including Card8, Card16, Gzma, Prf1, Il2rg, Il32, Cd52, and Ccl4 in CD4+ T cells isolated from patients with atherosclerosis." (PMID 36683148, 2023).
inflammatory bowel disease (3 papers, 2020 to 2023). A spectrum of small and large bowel inflammatory diseases of unknown etiology. "Herein we describe a novel mutation in the IL2RG gene in twin brothers associated with early-onset inflammatory bowel disease." (PMID 37461086, 2023). "Reported inflammatory conditions were surprisingly rare in reviewed patients carrying hypomorphic IL2RG mutations, with only three patients suffering from eczema or other skin rashes, two from inflammatory arthritis, two from interstitial lung disease, and one from inflammatory bowel disease." (PMID 32072341, 2020).
liver cancer (3 papers, 2020 to 2024). An epithelial or non-epithelial malignant neoplasm that arises from the liver. "Since IL2RB and IL2RG are sufficient to form functional receptor for transmitting signals from IL-229, liver cancer cells could also respond to IL-2 secreted by T cells and led to STAT5A activation." (PMID 38177099, 2024).
lymphoma (3 papers, 2012 to 2021). A malignant (clonal) proliferation of B- lymphocytes or T- lymphocytes which involves the lymph nodes, bone marrow and/or extranodal sites. "The disruption of the interleukin 2 receptor subunit gamma (IL2Rg) gene reduces the chance of spontaneous lymphoma development in these animals, which was a known problem in previous NOD/SCID models." (PMID 33802022, 2021). "The low incidence of spontaneous lymphomas in CIEA NOG mice is due to the knockout of the IL2Rg gene." (PMID 33802022, 2021).